LEP (leptin)
Diseases named in the same sentence as LEP in open-access papers (continued):
Sharing a sentence is not in itself a finding about the gene and the disease.
Obesity (continued). "The authors detected a significant interaction between leptin levels and obesity, hence concluded that obesity modifies the effect of leptin on kidney function decline in patients with type 2 diabetes." (PMID 27347436, 2015). "Despite the documented opposing roles of endocannabinoids and leptin in the control of feeding and obesity, only one study has examined the interplay between central leptin and endocannabinoid levels in humans." (PMID 25835291, 2015). "The purpose of this study was to determine if leptin treatment of INFH stimulates new bone formation to preserve femoral head shape in rats with diet-induced obesity." (PMID 25797953, 2015). "It is well documented that cognitive deficits are linked to obesity-related diseases, such as type II diabetes, and that individuals with obesity and type II diabetes display neuronal resistance to leptin even in the presence of high plasma leptin levels." (PMID 26464986, 2015). "Chronic HFD consumption results in central and peripheral leptin resistance, thereby preventing the neuroprotective role of leptin in obesity and potentially contributing to the downregulation of BDNF after chronic HFD consumption." (PMID 26260473, 2015). "Examples of genome-wide significant age-associated sites include CpG loci located in the promoter region of the obesity gene LEP, the childhood obesity gene OLFM4, the T2D gene IRS2, and the newly identified MetS gene TFAP2B." (PMID 25806089, 2015). "For obesity, these include genes functioning in the leptin-melanocortin pathway, such as the leptin (LEP) and melanocortin 4 receptor (MC4R) genes." (PMID 26363598, 2015). "In the current study, we report that LEP and ADIPOQ DNA methylation levels, measured in paired adipose tissues and blood samples, are associated with obesity-related anthropometric variables and fasting LDL-C levels." (PMID 25929254, 2015). "We conclude that the JNK/STAT3-signaling pathway induced by leptin is indeed involved in the mitochondrial dysfunction related to obesity in colon cancer cells." (PMID 26472027, 2015). "Our studies used mouse genetic approaches to inhibit the PKA pathway and this led to an increase in leptin sensitivity and resistance to diet-induced obesity." (PMID 26381935, 2015). "In obesity, leptin resistance or inadequate leptin action is indicated by high leptin level, and several mechanisms were postulated to explain the defect of leptin action in obese subjects." (PMID 26180527, 2015). "This mouse model exhibits persistent hyperphagia and obesity, resulting in hyperleptinemia, insulin resistance and increased leptin levels." (PMID 25825681, 2015). "The most frequently used rat and mouse models for obesity, metabolic syndrome, and T2D have defects in the leptin pathway." (PMID 25961053, 2015). "Leptin has a prominent role in the development and maintenance of acute and chronic inflammatory states such as rheumatoid arthritis (RA) and obesity." (PMID 26589684, 2015). "Our understanding of the interaction between leptin and hypothalamic energy balance genes has been gained primarily from studies under conditions of food deprivation or from genetic models of obesity." (PMID 25789758, 2015). "Obesity, specifically abdominal or visceral obesity, leads to high levels of pro-inflammatory adipokines including IL–6, IL–1β, leptin and TNF-alpha." (PMID 26437377, 2015). "Type 2 diabetes, hypertension, dyslipidemia and increased values of waist circumference, body fat, leptin, fibrinogen, IL-1β, hsCRP and TNFα were related to obesity (p < 0.05)." (PMID 25897330, 2015). "This study provides further evidence that LEP DNA methylation levels in blood cells and ADIPOQ DNA methylation levels in SAT are associated with obesity-related anthropometric measures." (PMID 25929254, 2015). "Some factors such as insulin-like growth factors, leptin, and steroid hormones seem to connect obesity and cancer, once they contribute to the development of the chronic inflammatory state." (PMID 26508818, 2015).
Obesity (continued). "The therapeutic potential of NUCB2/nesfatin-1 was discussed in several review articles, especially in the light of its leptin-independent signaling pathway, a hormone known to be less active under conditions of obesity (also known as leptin resistance)." (PMID 26635512, 2015). "Next, I will provide an overview of the central mechanisms for regulating body weight, including a discussion of central leptin/insulin resistance during aging and obesity." (PMID 26236282, 2015). "We examined the effects of leptin on revascularization and repair of the femoral head in rats with diet-induced obesity and INFH." (PMID 25797953, 2015). "Beneficial effects of leptin in obesity and neuroendocrine/metabolic dysfunction were reported only in rare cases of human congenital leptin deficiency." (PMID 26783391, 2015). "Obesity and insulin resistance, the hallmarks of T2D, lead to elevated leptin levels which in turn can result in tissue leptin resistance and endothelial dysfunction." (PMID 25716801, 2015). "Obesity is characterized by a chronic low-grade inflammation status, where different cytokines, including leptin, circulate at higher serum levels compared with a healthy weight status." (PMID 26053184, 2015). "Because leptin is a central negative regulator of body weight, it has been proposed as a treatment for obesity." (PMID 25918733, 2015). "In clinical studies, serum leptin concentrations are directly proportional to fat mass, and decreased central leptin responsiveness or leptin resistance is seen in obesity." (PMID 26110385, 2015). "This study provides mechanistic insight as to how obesity enhances the proliferation and metastasis of breast cancer cells; specifically, obASC-derived leptin contributes to the aggressiveness of breast cancer in obese women." (PMID 26286584, 2015). "As such, leptin is considered as a prominent catabolic hormone, since disruption of the gene coding for leptin (ob/ob mice) and/or its receptor (db/db mice) induces massive obesity, resulting from hyperphagia and reduced BAT thermogenesis." (PMID 26578907, 2015). "In obesity, its levels are increased; however, leptin resistance is observed, impairing leptin functions." (PMID 26697121, 2015). "Plasma leptin concentrations are significantly elevated in several rodent and human models of obesity in a proportional manner to adiposity." (PMID 26379553, 2015). "High fat diet induced obesity in mice leads to an overall increased body weight, pancreatic weight, serum leptin, and pancreatic tissue leptin levels." (PMID 25919692, 2015). "Given that leptin levels are increased in obesity and play an important proinflammatory role, strategies to attenuate leptin's effects on the immune system would be of great importance." (PMID 25918733, 2015). "Doubled effect of LEP resistance and obesity were reported to play an important role in altered sensitivity to preventive medication." (PMID 26783391, 2015). "Leptin has a wide range of functions from actingas an anti-obesity factor to an effective factor inreproduction, hematopoiesis, angiogenesis and Tlymphocytes system." (PMID 26246872, 2015). "While the cause of low GnRH release in obese patients is unclear, insulin and leptin resistance develops in some neuronal circuits during obesity in a manner similar to insulin resistance in peripheral tissues." (PMID 25946091, 2015). "Enhanced leptin production noted in prostate after intraprostatic formalin injection mimics the likely endocrine influence from obesity in prostatic inflammation." (PMID 25991911, 2015). "Since both leptin and adiponectin are increased in women compared to men, we next examined the leptin/adiponectin ratio as a method to better compare genders with regard to the role of adipokines in the pathogenesis of asthma in obesity." (PMID 26770217, 2015). "In recent years, leptin has emerged as a key candidate molecule mediating the molecular effects of obesity on cancer." (PMID 26359358, 2015).
Obesity (continued). "Leptin was also shown to directly activate SF1 neurons since selective deletion of the LEPR from these neurons induced obesity." (PMID 26578907, 2015). "The average increase in leptin levels was 7.9 ng/dL for gender (girls), 13.9 ng/dL for overweight, 26.4 ng/dL for obesity and 1.50 ng/dL for each unit of HOMA-IR." (PMID 26581745, 2015). "Although OB offspring had elevated plasma leptin they showed greater feed intake indicating maternal obesity induced leptin resistance." (PMID 25875659, 2015). "A recent basic study found that leptin can directly modulate autonomic function through the dorsomedial hypothalamus in relation to obesity." (PMID 26338087, 2015). "It has previously been reported that consumption of a high fat diet leads to obesity, insulin resistance and increased leptin levels by eighteen weeks of age in mice." (PMID 25919692, 2015). "In this study, we assessed the leptin level in children with ALL who developed obesity and overweight compared to patients with normal ranged BMI." (PMID 26705449, 2015). "For example, obesity, insulin resistance, and T2DM are associated with elevated level of leptin and decreased level of adiponectin, reflecting a state of leptin resistance and adiponectin deficiency." (PMID 25834745, 2015). "Leptin regulates feeding behavior; therefore rodents genetically lacking leptin or its receptor show hyperphagia and subsequently develop obesity and insulin resistance." (PMID 25793003, 2015). "Otherwise, we cannot rule out the possibility that histone modification, rather than DNA methylation, is the determinant elucidating the regulatory influence of n-3 PUFA on leptin expression in obesity." (PMID 26339623, 2015). "Hyperplasia or hypertrophy of adipose tissues plays a crucial role in obesity, which is accompanied by the release of leptin." (PMID 26593914, 2015). "Leptin has been shown to be involved in the sinusoidal endothelial dysfunction in obesity and neovascularization in NASH." (PMID 25658689, 2015). "Leptin, a major adipocytokine produced by adipocytes, is emerging as a key molecule linking obesity with breast cancer therefore, it is important to find effective strategies to antagonize oncogenic effects of leptin to disrupt obesity-cancer axis." (PMID 26359358, 2015). "Glucocorticoids and insulin act on adipocytes to increase leptin expression, possibly explaining the reason for increased leptin levels observed in obesity.On the other hand, fasting, testosterone, and thyroid hormone lead to a reduction in leptin expression." (PMID 26064110, 2015). "It is possible that obesity and leptin affect only specific types of prostate cancers or only certain events during tumour progression such as epithelial/mesenchymal transition, metastasis or angiogenesis." (PMID 26376613, 2015). "Levels in the circulation are known to correlate with body fat and higher leptin levels in obesity seem to be accompanied by leptin resistance." (PMID 26196519, 2015). "Other up-regulated genes that are also targets of miR-193 included mediators of obesity, related inflammatory cytokine and leptin signaling (JAK2) as well as atherosclerosis (SCARF2/SREC-I)." (PMID 26258540, 2015). "Recently adipose tissue derived hormone leptin together with other adipocytokines affect insulin sensitivity and is accepted to play a role in pathogenesis of obesity-related disorders." (PMID 26569494, 2015). "Further studies including obese patients and/or high pathophysiologic and pharmacologic leptin concentration will be necessary to address the relationship between leptin, glucose transport, and lymphocyte function in obesity." (PMID 25306890, 2015). "As we know more about how these cells participate in the control of food intake, the discovery of new therapeutical approaches to metabolic diseases, such as diabetes, obesity, or leptin resistance, looks increasingly plausible." (PMID 25859240, 2015).
Obesity (continued). "For example, IL-6 knockout mice develop obesity, elevated leptin, and altered glucose homeostasis with aging, suggesting that long-term IL-6 depletion can contribute to metabolic dysfunction." (PMID 26217222, 2015). "But, in most individuals, serum leptin levels are positively correlated with BMI and with indexes of obesity." (PMID 26581745, 2015). "The original design was to combine the defect in β-cell gene transcription that is found in lean and obese ZDF rats with the obesity of the Crl:CD (SD) model to produce an obese diabetic model that preserves the critical leptin pathway." (PMID 25961053, 2015). "Considering leptin activities other than satiety control, these models develop obesity and an average onset of T2DM pathology, with increased hyperglycemia, insulin resistance, and hyperlipidemia, in parallel with cardiac dysfunction." (PMID 25973429, 2015). "The expression of most pro-inflammatory adipokines, including leptin, is increased in obesity and this contributes to a “low grade inflammatory state”, which causes a variety of metabolic aberrations that affect joints and bone." (PMID 26210906, 2015). "Here, we explored the clinical impact of overweight/obesity on patient prognosis and leptin's effects on the metastatic potential of ovarian cancer cells." (PMID 26053184, 2015). "Two recent animal model studies support our findings and the role of leptin and obesity in high-grade serous ovarian cancers." (PMID 26053184, 2015). "One of the adipokines released by adipocytes is leptin, and serum leptin concentrations are increased in obesity." (PMID 26542296, 2015). "Many of the known monogenic forms of obesity, affecting appetite regulation through hypothalamic pathways, including the leptin-melanocortin pathway, were first identified from murine models of obesity." (PMID 26120850, 2015). "Acute hyperleptinemia induced vasodilatory effects and this seemingly contradicts the coexisting hypertension and increased leptin levels on obesity." (PMID 25650072, 2015). "Prior to the onset of overt obesity, increased adipocyte size was associated with elevated expression levels of factors promoting lipogenesis (i.e., SREBP1c, FAS, leptin) in weanling pups and adult offspring from FR dams." (PMID 26029119, 2015). "Adipokines, for example, adiponectin and leptin, play crucial roles in multiple processes such as inflammation, metabolism, insulin resistance, and obesity-related conditions." (PMID 25834745, 2015). "Leptin resistance is one potential mechanism producing obesity and is a key event in the onset of negatively altered energy homeostasis." (PMID 25875659, 2015). "Reduction of sLepR levels occur in progression of obesity with fat mass accumulation, turns into more bioactive leptin for signaling through transmembrane receptors." (PMID 26589684, 2015). "It was shown that obesity, leptin levels and adipocyte size can be reduced by rapamycin, an immunosuppressive chemical able to bind mTOR Complex 1 (mTORC1) and inhibit downstream signaling." (PMID 25857300, 2015). "To date, adipokine modulation of immune function by leptin is the best-characterized link between obesity and immune function." (PMID 26184280, 2015). "The hormone leptin is increased with obesity, and genetic models have shown that leptin can negatively influence bone mass indirectly via serotonin suppression in the central nervous system." (PMID 25861094, 2015). "Plasma circulating leptin levels directly correlate to total body fat mass and increase proportionally in obesity." (PMID 25306890, 2015). "In contrast to leptin, adiponectin levels are decreased in obesity and tend to increase in starvation." (PMID 26770217, 2015). "The leptin (LEP) and leptin-receptor (LEPR) genes have been studied to find gene variants potentially related to the pathophysiology of obesity, T2DM, and their associated complications." (PMID 26064921, 2015).
Obesity (continued). "High-fat diet-induced obesity or chronic leptin infusion are correlated with increased arterial blood pressure." (PMID 25793389, 2015). "Leptin, a 16kDa peptide hormone, is predominantly secreted by the adipose tissue, which regulates obesity and is one of the factors contributing to IDD." (PMID 25892402, 2015). "This phenomenon suggests there is an additive effect of chronic inflammation resulting from RA and obesity in which leptin favors the humoral response against citrullinated proteins." (PMID 26589684, 2015). "In this context, it would be important to further explore any correlation between the clinical response to KBG and leptin resistance in obesity patients." (PMID 25793003, 2015). "Leptin serum concentration, instead, is typically increased in both obesity and CKD, and mice over-expressing leptin are at increased risk of CKD." (PMID 25710704, 2015). "There was a significant increasing trend in AEA, 2-AG, WC (P<0.001), insulin (P = 0.005), HOMA-IR (P = 0.004), leptin (P = 0.008), hsCRP (P = 0.002), along the three degrees of obesity." (PMID 26561012, 2015). "As molecular effects of obesity are largely mediated by adipocytokine leptin, finding effective novel strategies to antagonize neoplastic effects of leptin is desirable to disrupt obesity-cancer axis." (PMID 26036628, 2015). "Leptin is mainly synthesized by the subcutaneous adipose tissue and its plasma levels increase with the weight gain, suggesting that common human obesity is a leptin-resistant state." (PMID 25129652, 2015). "Among the patients with severe, early-onset obesity, the carriers of a homozygous mutation in the leptin gene (LEP) can be treated with recombinant leptin therapy, which leads to a marked and sustained reduction in weight." (PMID 26599467, 2015). "Increased food intake and IR have been shown to increase plasma leptin levels and lead to leptin resistance in tissue, which is very common in obesity and MetX." (PMID 26413164, 2015). "Leptin has been identified as a key member of the obesity-breast cancer molecular network influencing several aspects of breast cancer initiation, growth, metastatic progression as well as response to therapy." (PMID 26036628, 2015). "Animal models of obesity support this with leptin resistance in the hypothalamus shown to decrease satiety but preserve sympathetic activity." (PMID 26064978, 2015). "Since TNBC lacks expression of hormone receptors, distinct molecular mechanisms must link obesity to this subtype of breast cancer, for example insulin resistance, secretion of pro-angiogenic adipokines such as leptin, and chronic inflammation." (PMID 26684197, 2015). "In another study both obesity and increased plasma leptin concentration correlated with high blood pressure." (PMID 26783391, 2015). "High leptin and low adiponectin are thought to contribute to asthma in obesity through a number of different pathways." (PMID 26610598, 2015). "Further studies are necessary to address the relationship between leptin, glucose transport and the lymphocytes’ function in obesity." (PMID 25306890, 2015). "Moreover, peritumoral adipose tissue with increased cell size (a hallmark of obesity) may be a permissive milieu for local tumor invasiveness, and we showed that an increased secretion of leptin is strongly associated with alterations in the mRNA levels of key regulator genes of tumor progression." (PMID 25857300, 2015). "Further experiments using programmed insulin and leptin administration and monitoring, combined with planned diet regimes, can improve our understanding about progression of metabolic diseases like obesity and diabetes." (PMID 26540285, 2015). "Development of the ZDSD rat model was undertaken to produce a model that expresses polygenic obesity and diabetes with an intact leptin pathway." (PMID 25961053, 2015).